BCKDHB (branched chain keto acid dehydrogenase E1 subunit beta)
Description:
Together with BCKDHA forms the heterotetrameric E1 subunit of the mitochondrial branched-chain alpha-ketoacid dehydrogenase (BCKD) complex. The BCKD complex catalyzes the multi-step oxidative decarboxylation of alpha-ketoacids derived from the branched-chain amino-acids valine, leucine and isoleucine producing CO2 and acyl-CoA which is subsequently utilized to produce energy. The E1 subunit catalyzes the first step with the decarboxylation of the alpha-ketoacid forming an enzyme-product intermediate. A reductive acylation mediated by the lipoylamide cofactor of E2 extracts the acyl group from the E1 active site for the next step of the reaction.
Synonyms: BCKDE1B; BCKDH E1-beta; OVD1B; E1B; MSUD1B
Tractability: Small molecule: a structure with a bound ligand is known; it has a binding pocket of medium quality. PROTAC: ubiquitination databases record sites on it; its protein half-life has been measured.
Target class: Enzyme; Oxidoreductase
Gene: Protein-coding gene on chromosome 6 (80,106,647 to 80,351,082, forward strand). Ensembl gene ENSG00000083123.
Subcellular location: Mitochondrion matrix
Subcellular location (Human Protein Atlas): Mitochondria; Nucleoli; Nucleoplasm
Pathways (Reactome):
Disease: Branched-chain ketoacid dehydrogenase kinase deficiency; H139Hfs13* PPM1K causes a mild variant of MSUD; Loss-of-function mutations in BCKDHA or BCKDHB cause MSUD; Loss-of-function mutations in DBT cause MSUD2; Loss-of-function mutations in DLD cause MSUD3/DLDD
Metabolism: BCKDH synthesizes BCAA-CoA from KIC, KMVA, KIV; Branched-chain amino acid catabolism
Gene Ontology:
Molecular function: branched-chain 2-oxo acid dehydrogenase activity; protein binding
Biological process: branched-chain alpha-keto acid decarboxylation to branched-chain acyl-CoA; branched-chain amino acid catabolic process; response to nutrient; L-isoleucine catabolic process; L-leucine catabolic process; L-valine catabolic process
Cellular component: branched-chain alpha-ketoacid dehydrogenase complex; mitochondrion; mitochondrial matrix; protein-containing complex
Genetic constraint (gnomAD): Loss-of-function variants: 35 observed, 38.49 expected, observed/expected ratio (o/e) 0.91, 90% interval 0.69 to 1.21. The upper end of that interval is the gene's LOEUF score, 1.21, which puts it in group 5 of 6, group 1 being the genes least tolerant of losing a copy. Missense variants: 446 observed, 446.26 expected, observed/expected ratio (o/e) 1, 90% interval 0.92 to 1.08. Synonymous variants: 186 observed, 161.84 expected, observed/expected ratio (o/e) 1.15, 90% interval 1.02 to 1.3.
Gene-disease validity (ClinGen):
ClinGen rates the evidence that BCKDHB causes each of these diseases.
maple syrup urine disease type 1B (autosomal recessive): Definitive. A maple syrup urine disease caused by mutations in BCKDHB.
Homologues: Orthologues: macaque BCKDHB (98% identical), rabbit BCKDHB (94% identical), pig BCKDHB (93% identical), rat Bckdhb (92% identical), mouse Bckdhb (91% identical), guinea pig BCKDHB (91% identical), chimpanzee BCKDHB (91% identical), tropical clawed frog bckdhb (80% identical), zebrafish bckdhb (77% identical), Caenorhabditis elegans bckd-1B (59% identical), Drosophila melanogaster BckdhB (58% identical). Paralogues in human: PDHB (32% identical), TKT (25% identical), TKTL2 (23% identical), TKTL1 (22% identical).
Diseases named in the same sentence as BCKDHB in open-access papers:
BCKDHB is named in the same sentence as 22 diseases in open-access papers, as found by Europe PMC text mining. Sharing a sentence is not in itself a finding about the gene and the disease. The quoted sentences say what the papers report.
maple syrup urine disease (20 papers, 2013 to 2025). An autosomal recessive inherited disorder caused by mutations in the BCKDHA, BCKDHB, DBT, and DLD genes. "The confirmation of maple syrup urine disease diagnosis involves identifying pathogenic variants in the BCKDHB gene." (PMID 38660376, 2024). "Mutations in the BCKDHB gene are known to be responsible for the maple syrup urine disease (Online Mendelian Inheritance in Man #248600) characterized by mental and physical retardation, feeding problems, and a maple syrup odor of the urine." (PMID 28644415, 2017). "Similarly, mutations in BCKDHB gene (high DAF in CEU & CHB) are linked to cases of maple syrup urine disease, only in the Chinese and Korean populations." (PMID 27586304, 2016). "Pathogenic biallelic variants in the BCKDHA, BCKDHB, or DBT genes are responsible for the inborn error of metabolism known as Maple Syrup Urine Disease (MSUD)." (PMID 40710547, 2025). "Maple syrup urine disease (MSUD) is an autosomal recessive inherited metabolic disorder caused by mutations in the BCKDHA, BCKDHB, DBT, and DLD genes." (PMID 29740478, 2018). "The alternative direct prediction of genes for oligogenic diseases with RWR (e.g. predicting DBT gene as associated to maple syrup urine disease using only BCKDHA and BCKDHB genes as seed) yielded an AUC of 0.85." (PMID 28715999, 2017). "Maple syrup urine disease is associated with mutation in DBT, BCKDHB, and BCKDHA genes." (PMID 25029527, 2014). "Maple syrup urine disease (MSUD) is a rare autosomal recessive metabolic disorder caused by variants in any of the following genes: BCKDHA, BCKDHB, and DBT gene." (PMID 39456016, 2024). "Sequence analysis of the three maple syrup urine disease (MSUD) genes, BCKDHA, BCKDHB, or DBT, in two unrelated cases of known biochemical diagnosis of MSUD detected only one familial mutation each." (PMID 24304607, 2013). "Maple syrup urine disease (MSUD) is an autosomal recessive metabolic disorder originating from defects in the branched-chain α-ketoacid dehydrogenase (BCKDH) complex encoded by BCKDHA, BCKDHB and DBT." (PMID 38837343, 2024). "Maple syrup urine disease (MSUD) is an autosomal recessive disorder of branched chain amino acid (leucine, valine, isoleucine) catabolism due to branched-chain alpha-ketoacid dehydrogenase complex (BCKD) deficiency encoded by BCKDHA, BCKDHB, and DBT genes." (PMID 32752260, 2020). "For example, among the 19 diseases with ‘Ketosis’ as clinical sign, two of them were classified as oligogenic: maple syrup urine disease with 3 genes (BCKDHA, BCKDHB and DBT) and Permanent neonatal diabetes mellitus with 4 genes (GCK, INS, KCNJ11 and ABCC8)." (PMID 28715999, 2017).
breast carcinoma (1 paper, 2025). "Notably, previous research found BCKDHB expression to be upregulated in breast cancer compared to normal tissue." (PMID 39886381, 2025).
Hyperglycemia (1 paper, 2025). An increased concentration of glucose in the blood. "As revealed by protein quantification, BCKDHA and BCKDHB were downregulated in diabetic retinas and hyperglycemia-induced Müller cells, whereas BCKDK levels increased." (PMID 39150511, 2025).
lung adenocarcinoma (1 paper, 2022). A carcinoma that arises from the lung and is characterized by the presence of malignant glandular epithelial cells. "The low expression of several enzymes, such as BCKDHB, ACADSB and HMGSC2, was correlated with worse patient survival in lung adenocarcinomas." (PMID 36433955, 2022).
sarcopenia (1 paper, 2025). Progressive decline in muscle mass due to aging which results in decreased functional capacity of muscles. "2.In sarcopenia patients, the BCAT2 and BCKDHB genes involved in BCAA metabolism are significantly downregulated, and the levels of the key enzymes BCAT2 and BCKDHB are markedly reduced." (PMID 41568005, 2025).
Sepsis (1 paper, 2023). Sepsis is defined as life-threatening organ dysfunction caused by a dysregulated host response to infection. "The results of qPCR showed that the expression of NDUFB3 was higher in sepsis, whereas the expression of LETMD1 and BCKDHB were lower in SP than in HC." (PMID 37228596, 2023).
type 2 diabetes (1 paper, 2017). "When compared to BMI-matched obese controls, type 2 diabetes is characterized by reduced expression of genes encoding for the mitochondrial steps of BCAA metabolism BCAT2, and BCKDHB (encoding the E1beta subunit of BCKD)." (PMID 29062026, 2017). "In type 2 diabetes of older subjects a reduced expression was also detected for BCKDHB." (PMID 29062026, 2017).
metabolic disorder (5 papers, 2018 to 2024). "Homozygous mutations of the human orthologue, BCKDHB, cause MSUD [MIM 248600], an inborn metabolic disease with an autosomal recessive pattern of inheritance." (PMID 29703985, 2018).
BCKDHB also shares sentences with these, for which no sentence is quoted: cancer (2 papers); tumor (2); biotinidase deficiency (1); crescentic glomerulonephritis (1); diabetes (1); Hartnup disease (1); Insulin resistance (1); Methylmalonic aciduria (1); neonatal diabetes mellitus (1); nonalcoholic fatty liver disease (1); nonalcoholic steatohepatitis (1); pontocerebellar hypoplasia type 6 (1); Skeletal muscle atrophy (1); type I citrullinemia (1).